CRLS1 (cardiolipin synthase 1)
Description:
Catalyzes the synthesis of cardiolipin (CL) (diphosphatidylglycerol) by specifically transferring a phosphatidyl group from CDP-diacylglycerol to phosphatidylglycerol (PG). CL is a key phospholipid in mitochondrial membranes and plays important roles in maintaining the functional integrity and dynamics of mitochondria under both optimal and stress conditions.
Synonyms: CLS; C20orf155; CLS1; dJ967N21.6; GCD10; COSPD57
Tractability: Antibody: UniProt predicts a signal peptide or a membrane-spanning region. PROTAC: ubiquitination databases record sites on it; its protein half-life has been measured.
Gene: Protein-coding gene on chromosome 20 (6,006,052 to 6,040,053, forward strand). Ensembl gene ENSG00000088766.
Subcellular location: Mitochondrion inner membrane
Pathways (Reactome):
Metabolism: Acyl chain remodelling of PG; Synthesis of CL
Gene Ontology:
Molecular function: cardiolipin synthase (CMP-forming); 1-acylglycerol-3-phosphate O-acyltransferase activity; 2-acylglycerol-3-phosphate O-acyltransferase activity; phosphotransferase activity, for other substituted phosphate groups
Biological process: cardiolipin biosynthetic process; phosphatidylglycerol acyl-chain remodeling; phospholipid biosynthetic process
Cellular component: mitochondrial inner membrane; mitochondrion; mitochondrial membrane; membrane
Genetic constraint (gnomAD): Loss-of-function variants: 11 observed, 7.76 expected, observed/expected ratio (o/e) 1.42, 90% interval 0.87 to 1.91. That is too few expected variants to judge how well the gene tolerates losing a copy. Missense variants: 188 observed, 129.52 expected, observed/expected ratio (o/e) 1.45, 90% interval 1.29 to 1.64. Synonymous variants: 75 observed, 58.29 expected, observed/expected ratio (o/e) 1.29, 90% interval 1.07 to 1.56.
Gene-disease validity (ClinGen):
ClinGen rates the evidence that CRLS1 causes each of these diseases.
mitochondrial disease (autosomal recessive): Moderate.
Homologues: Orthologues: mouse Crls1 (86% identical), guinea pig CRLS1 (82% identical), pig CRLS1 (72% identical), rat Crls1 (69% identical), chimpanzee CRLS1 (66% identical), rabbit CRLS1 (64% identical), tropical clawed frog crls1 (58% identical), zebrafish crls1 (58% identical), Drosophila melanogaster CLS (35% identical), Caenorhabditis elegans crls-1 (32% identical). Paralogues in human: HDHD5 (16% identical).
Diseases named in the same sentence as CRLS1 in open-access papers:
CRLS1 is named in the same sentence as 46 diseases in open-access papers, as found by Europe PMC text mining. Sharing a sentence is not in itself a finding about the gene and the disease. The quoted sentences say what the papers report.
Insulin resistance (6 papers, 2018 to 2025). Increased resistance towards insulin, that is, diminished effectiveness of insulin in reducing blood glucose levels. "We identified a rare (minor allele frequency 0.05%) synonymous variant in CRLS1 (rs149380663) that is positively associated with multiple indicators of insulin resistance and negatively associated with measures of insulin sensitivity." (PMID 29861389, 2018). "We further identify a rare human CRLS1 variant associated with insulin resistance and show that adipose CRLS1 levels positively correlate with insulin sensitivity." (PMID 29861389, 2018). "Our discoveries of a CRLS1 variant associated with insulin resistance and reduced CRLS1 levels in fat from diabetic patients indicate that CL biosynthesis in adipose tissue could contribute to glycemic balance in humans." (PMID 29861389, 2018). "By reducing the expression and activity of ATF3, CRLS1 reduces insulin resistance, hepatic steatosis, inflammation, and fibrosis during the pathological phase of non-alcoholic steatohepatitis (NASH)." (PMID 35677823, 2022). "The CRLS1 mRNA levels in human scWAT negatively correlated with HOMA2 measures of insulin resistance and positively correlated with HOMA2 measures of insulin sensitivity." (PMID 29861389, 2018). "Particularly, CRLS1, a primary mediator in the activation and recruitment of thermogenic fat correlates positively with insulin sensitivity and could reduce insulin resistance in MetS." (PMID 32340411, 2020). "By decreasing ATF3, cardiolipin synthase 1 (CRLS1), a member of the cytidine diphosphate-alcohol phosphatidyl transferase class-I family, decreases insulin resistance, hepatic steatosis, inflammation, and fibrosis." (PMID 39911797, 2025).
lung carcinoma (6 papers, 2021 to 2023). "Studies have found that the lncRNA PELATON in lung cancer targets the miR-7-5p/CRLS1 axis to inhibit cell proliferation and induce apoptosis." (PMID 37936118, 2023). "The long-chain noncoding RNA LINC01272 inhibits the proliferation of lung cancer cells and promotes apoptosis by modulating the miR-7-5p/CRLS1 signaling axis." (PMID 36532744, 2022). "LINC01272 in lung cancer inhibits multiplication and induces programmed cell death via the miR-7-5p/CRLS1 pathway, and hypoexpression of LINC01272 corresponds to poor prognosis." (PMID 35915656, 2022).
Hepatic steatosis (4 papers, 2022 to 2025). Steatosis is a term used to denote lipid accumulation within hepatocytes. "Additionally, peripheral blood leukocyte ACSL4, CRLS1, CTP1A, SIGIRR, SSBP1, and ZNF622 genes containing DMPs might be used as serum biomarkers to stratify NAFLD patients into groups with simple hepatic steatosis and NASH." (PMID 35433752, 2022).
non-small cell lung carcinoma (3 papers, 2022 to 2024). A group of at least three distinct histological types of lung cancer, including non-small cell squamous cell carcinoma, adenocarcinoma, and large cell carcinoma. "A study of cardiolipin metabolism suggested the tumor suppressor activity of CRLS1 in non-small cell lung cancer, and hepatocellular carcinoma." (PMID 36338962, 2022).
breast carcinoma (2 papers, 2021 to 2024). "As proof of principle validation, we show that alternative alleles facilitate 3′ untranslated region lengthening of CRLS1 gene leading to increased protein abundance and promoted proliferation of breast cancer cells." (PMID 38409266, 2024). "These experimental results are in line with our 3′aTWAS analysis result, which suggested that the usage of long 3′UTR of CRLS1 increases breast cancer risk (Z-score = 6.10 in breast mammary tissue)." (PMID 38409266, 2024). "In particular, our investigations revealed a 3′aTWAS association for CRLS1 in breast cancer, a finding that was validated through experimental evidence." (PMID 38409266, 2024). "To validate the predicted effects of 3′aQTLs on 3′UTR usage, we experimentally validated the genetic regulation of CRLS1 in breast cancer." (PMID 38409266, 2024). "Former studies have demonstrated that anti-cardiolipin antibodies elevated thrombosis rate in breast cancer and CRLS1 was taken as a tumor suppressor of NSCLC." (PMID 34099597, 2021).
breast adenocarcinoma (1 paper, 2022). "Low nucleosome occupancy that corresponds to large nucleosome-free regions were detected at TSSs of CDT1, CRLS1, and SNX13 in chronic myelogenous leukemia cells, and at TSSs of POC1A, and CRLS1in breast adenocarcinoma cells." (PMID 36338962, 2022).
heart failure (1 paper, 2023). Inability of the heart to pump blood at an adequate rate to meet tissue metabolic requirements. "Decreased cardiac mitochondrial cardiolipin and CRLS1 content occurs as a consequence of DOX treatment, and alterations to cardiolipin content are associated with heart failure." (PMID 37175395, 2023).
liver cancer (1 paper, 2021). An epithelial or non-epithelial malignant neoplasm that arises from the liver. "As a potential therapeutic target, silencing of CRLS1 inhibited cell growth in liver cancer." (PMID 34258555, 2021).
lung injury (1 paper, 2025). "In the context of acute lung injury, PINK1 was shown to bind to and degrade cardiolipin synthase 1 (CRLS1) and decrease overall CL expression resulting in dysfunctional mitochondria and increased programmed cell death." (PMID 40615437, 2025).
Mitochondrial encephalopathy (1 paper, 2022). "Here, we report four individuals, including two siblings, affected by a progressive mitochondrial encephalopathy with biallelic variants in the cardiolipin biosynthesis gene CRLS1." (PMID 35147173, 2022).
optic atrophy (1 paper, 2026). A disorder characterized by loss of optic nerve fibers. "Mutations in CRLS1 are associated with developmental encephalopathy, optic atrophy, and hearing loss." (PMID 41277110, 2026). "Mutations in PTPMT1, similar to CRLS1, are linked to neurodevelopmental syndromes where patients present with cerebellar ataxia, optic atrophy, epilepsy, and bulbar dysfunction; specifically, bi-allelic variants have impaired production of cardiolipin." (PMID 41277110, 2026).
ovarian carcinoma (1 paper, 2022). A malignant neoplasm originating from the surface ovarian epithelium. "Although LIMCH1, CRLS1, CDT1, CNIH4 have been associated with various cancers, their relationship with ovarian cancer has been proposed in this study for the first time to the best of our knowledge." (PMID 36338962, 2022). "As a result, six genes (CDT1, CNIH4, CRLS1, LIMCH1, POC1A, and SNX13), and two miRNAs (mir-147a, and mir-103a-3p) were suggested as novel candidate prognostic biomarkers for ovarian cancer." (PMID 36338962, 2022). "Furthermore, LIMCH1, CRLS1, CDT1, and CNIH4 were found to be associated with various cancer types, but their roles in ovarian cancer have not been identified yet." (PMID 36338962, 2022).
sarcopenia (1 paper, 2024). Progressive decline in muscle mass due to aging which results in decreased functional capacity of muscles. "Although the specific signaling pathway remains elusive, Crls1 has promising potential for ameliorating sarcopenia by influencing muscle regeneration processes." (PMID 38556544, 2024).
tumor (10 papers, 2016 to 2025). "According to previous studies, CRLS1 can also be used as a tumor suppressor to decrease thrombogenesis in tumors." (PMID 36532744, 2022). "The study of CL metabolism proposes a tumor suppressor implication of the CL biosynthesis gene, CRLS1." (PMID 33126604, 2020). "More studies also propose the tumor suppressor activity of CRLS1 in HCC." (PMID 33126604, 2020). "Based on metabolic modeling analysis, we identified four target genes, namely SOAT1, CRLS1, ACACB, and GPD2, whose inhibition can block the growth of ccRCC tumor cells with relatively low toxicity to normal tissue cells." (PMID 34258555, 2021).
cancer (4 papers, 2013 to 2022). A tumor composed of atypical neoplastic, often pleomorphic cells that invade other tissues. "RNAi-mediated knockdown of cardiolipin synthase (CLS1; gene name CRLS1) is sufficient to release cytochrome c from the inner mitochondrial membrane, and sensitizes cancer cells to apoptotic stimuli." (PMID 23326511, 2013). "CRLS1 is not the only CL metabolism enzyme that could be involved in cancer." (PMID 33126604, 2020).
mitochondrial disease (2 papers, 2022 to 2024). "Using patient-derived fibroblasts, we characterized cardiolipin synthase 1 (CRLS1) dysfunction that impaired mitochondrial morphology and biogenesis, providing functional evidence that the CRLS1 variants cause mitochondrial disease." (PMID 35147173, 2022).
myopathy (2 papers, 2024 to 2025). A disease of the muscle in which the muscle fibers do not function properly. "Specifically, age-dependent loss of CRLS1 contributes to impaired muscle regeneration and the development of myopathy." (PMID 38556544, 2024).
infection (1 paper, 2024). The state of being infected such as from the introduction of a foreign agent such as serum, vaccine, antigenic substance or organism. "After infection with AAV9-shCrls1, significant reductions in Crls1 mRNA and total CL levels were observed in the TA muscles." (PMID 38556544, 2024).
metabolic disease (1 paper, 2018). A congenital disorder (due to inherited enzyme abnormality) or acquired (due to failure of a metabolically important organ) disorder resulting from an abnormal metabolic process. "Therefore, we directly investigated whether altered CRLS1 levels in human adipose tissue were linked to metabolic disease." (PMID 29861389, 2018).
CRLS1 also shares sentences with these, for which no sentence is quoted: Nephroblastoma (4 papers); hepatocellular carcinoma (2); bacterial infection (1); Barth syndrome (1); brain tumors (1); cardiomyopathy (1); cerebellar ataxia and (1); cervical carcinoma (1); chronic myelogenous leukemia (1); ciliopathy (1); dilated cardiomyopathy with (1); Encephalopathy (1); glioma (1); Joubert syndrome (1); kidney tumor (1); lung adenocarcinoma (1); MEGDEL syndrome (1); metabolic syndrome (1); neutropenia (1); Obesity (1); peripheral neuropathy (1); Progressive encephalopathy (1); rhabdoid kidney tumor (1); sarcoma (1); scrapie (1); Sengers syndrome (1); skin melanoma (1).